ALB (albumin)
Diseases named in the same sentence as ALB in open-access papers (continued):
Sharing a sentence is not in itself a finding about the gene and the disease.
malnutrition (continued). "This study revealed that AECOPD patients with malnutrition had lower serum ALB levels than those without malnutrition." (PMID 39050134, 2024). "The deceased group did not have a significantly longer LOS compared to non-deceased patients (p = 0.115); serum albumin and lymphocyte values are indicators of a malnutrition state, which correlate with poor clinical outcomes in patients." (PMID 38732604, 2024). "Patients with low ALB may have elevated ALP, reduced immunity, malnutrition and increased treatment resistance." (PMID 38552093, 2024). "ALB is frequently used to diagnose malnutrition, but there is a lack of evidence-based clinical guidelines supporting its application in specific conditions and settings." (PMID 38622502, 2024). "Patients without malnutrition (the “NO” group) exhibited significantly better laboratory values of HB, lymphocytes, TP, and ALB compared to those with malnutrition." (PMID 39085739, 2024). "Despite a much younger patient cohort, with fewer co-morbidities, we found that malnutrition is common among CKD patients at the largest renal unit in the country, and higher serum albumin, creatinine, MUAC, body cell mass, and being employed were all protective against malnutrition." (PMID 38866974, 2024). "A total MNA score below 24 shows malnutrition, with poor nutritional intake, but without weight loss, or low albumin level, while patients with MNA scores ≤17 probably have low albumin levels and experience weight loss." (PMID 38674893, 2024). "Serum albumin and prealbumin declines should be recognized as inflammatory markers rather than direct indicators of malnutrition." (PMID 39497710, 2024). "Similarly, the latent variable serum protein status was summarized by total protein, albumin, and SAA, which are important parameters in the diagnosis of acute inflammation, infection, and malnutrition." (PMID 37917250, 2024). "After the bivariate analysis to assess the individual influence of factors on the development of malnutrition and inflammation, the combined analysis resulted in the following significant factors: gender, age, AMC measurement, serum albumin level, and time on HD." (PMID 39284026, 2024). "Serum GDF15 levels in patients with malnutrition and AECOPD were significantly higher than those in patients without malnutrition, whereas the serum ALB levels were significantly lower than those in patients without malnutrition (p < 0.001)." (PMID 39050134, 2024). "The changes characteristic of malnutrition are not statistically significant, and the albumin values, although low, are within the reference range." (PMID 39062797, 2024). "Of note, prior studies have demonstrated that laboratory values of albumin or pre‐albumin are not specific for malnutrition, and their use has fallen out of favor." (PMID 38982534, 2024). "The albumin (ALB) level was lower in the malnutrition group than in the non-malnutrition group, while the C-reactive protein (CRP) level was higher; these differences were also statistically significant (P < 0.05)." (PMID 39070256, 2024). "PNI determined by the number of LYM in peripheral blood and serum ALB showed statistically significantly different values between the preDM and T2DM group, as well as the fact that patients with T2DM had a moderate-to-severe malnutrition status at diagnosis." (PMID 39682569, 2024). "It has been reported that albumin acts as a negative acute‐phase reactant, with its serum levels typically decreasing in situations involving inflammation or malnutrition." (PMID 38402549, 2024). "A limitation of this study is that the malnutrition of the patients was evaluated using serum albumin, which can be affected by many other non-nutritional factors (disease, hospitalization, or therapeutic treatments)." (PMID 39519455, 2024). "Because albumin is a negative acute phase reactant and levels decrease in patients with inflammation, hypoalbuminemia can be a result of malnutrition or simply a reflection of inflammatory states." (PMID 38474780, 2024).
malnutrition (continued). "Since the threshold value of 3.5 g/dL albumin is also used as an indicator for malnutrition, no conclusion can be drawn about the nutritional status." (PMID 37571292, 2023). "Serum albumin level was statistically lower in the group with malnutrition than that in the group without malnutrition (3.4 ± 0.3 g/dL vs. 3.9 ± 0.4 g/dL, p < 0.001)." (PMID 37791200, 2023). "The moderate or severe malnutrition group showed reduced hemoglobin, triglyceride, and low density lipoprotein (LDL) cholesterol, as well as decreased CONUT score indexes (albumin, total cholesterol, and lymphocyte count), and elevated BNP and NT-proBNP amounts." (PMID 36824173, 2023). "Therefore, albumin serves as the denominator in the AAR index, in order to correct for malnutrition status and background glycemia." (PMID 37745131, 2023). "In cases of malnutrition due to acute or subacute pathology, classical parameters such as weight, BMI, albumin, and prealbumin are often not useful." (PMID 38075215, 2023). "Altered level of serum albumin, TP and Hgb was correlated with the SGA tool of malnutrition." (PMID 36869395, 2023). "Four components—body mass index, normalized protein catabolic rate, normalized serum creatinine level, and serum albumin level—constitute the simple PEW score; this score was calculated based on the positive number of items concerning malnutrition among these four components." (PMID 37652929, 2023). "There is no gold standard for clinical evaluation of malnutrition, and commonly used indicators to evaluate nutritional status include BMI and albumin, but they do not adequately reflect the nutritional status of patients." (PMID 37599357, 2023). "With an increasing emphasis on the role of inflammation in malnutrition in dialysis patients, MIS is derived from SGA and includes three new parameters: BMI, serum albumin level, and total iron binding capacity, which makes it a more comprehensive evaluation system than SGA." (PMID 37038353, 2023). "In malnutrition–inflammation complex syndrome, a strong relationship is seen between increased levels of inflammatory markers, low albumin levels, and malnutrition, although the exact definition of malnutrition is not standardized." (PMID 36977352, 2023). "Confounding was taken into account by adjusting for key factors, including malnutrition based on albumin level, not usually available in registry studies, and BMI." (PMID 36882628, 2023). "Especially in recent work, the role of serum biomarkers, particularly serum albumin, in diagnosing or monitoring malnutrition is controversial, mainly due to its lack of specificity and long half-life (approximately 20 days)." (PMID 37892441, 2023). "Therefore, we decided to choose the studies, which took serum albumin < 3.5 g/dl, and NRS score < 3 (which has been proved to be comparable), as a marker of pre-operative malnutrition." (PMID 37256389, 2023). "Regarding nutritional indicators, the albumin (ALB) level in the study group surpassed that observed in the control group, suggesting that immunonutrients might be instrumental in ameliorating malnutrition." (PMID 37960219, 2023). "As far as albumin is concerned, its trend rather than the single value must be considered with a downward trend indicating malnutrition." (PMID 37513579, 2023). "In the present study, both groups had similar levels of albumin and no malnutrition, a probable result of the close support of a dietitian and the use of a standard 200-cm biliopancreatic limb length." (PMID 36161607, 2022). "We also did not use a modified BMI (considering the serum albumin levels), which is a useful biomarker in malnutrition status." (PMID 36672570, 2022). "Subjects with malnutrition according to the criteria of MNA-SF (score ≤ 7; average albumin 36.38 ± 2.98 g/L) were recruited for probiotic supplementation lasting for 12 weeks from mid-October to mid-January, and with continuous observation for another 12 weeks after probiotic discontinuation." (PMID 36079806, 2022).
malnutrition (continued). "Even though, historically, albumin was thought to be a malnutrition marker, it is known that albumin is a negative acute phase protein." (PMID 36014955, 2022). "Serum albumin is a negative acute-phase reactant and, as a marker of malnutrition, is part of the frailty criteria." (PMID 35244369, 2022). "While there are concerns regarding the effects of a plant-based diet on total energy and protein intake; malnutrition; and serum potassium, phosphorus, and albumin, these have not been borne out by available data." (PMID 35334961, 2022). "Low serum albumin is a strong predictor of mortality, but this does not necessarily equate to a diagnosis of malnutrition." (PMID 36014879, 2022). "Additionally, patients with malnutrition (according to the GLIM criteria) presented with decreased phase angle (PA) and standardized PA (SPA), decreased serum levels of albumin, transferrin and total cholesterol, accompanied by increased serum RCP and IL6." (PMID 35158762, 2022). "Clinical and nutritional monitoring was performed by malnutrition-inflammation score (MIS), biochemical parameters (s-albumin, s-prealbumin, and serum C-reactive protein (s-CRP), body composition measured by bioelectrical impedance analysis (BIA), anthropometry, and handgrip strength measurements." (PMID 36145223, 2022). "BAR can be evaluated as a comprehensive body reserve by considering the four conditions of malnutrition, dehydration, liver reserve, and kidney reserve and may be more useful than BUN or serum albumin in assessing disease severity." (PMID 36407534, 2022). "Fourth, malnutrition was only defined by serum albumin, not including prealbumin, serum cholesterol, body mass, or muscle." (PMID 35938138, 2022). "Hypoalbuminemia does not directly indicate malnutrition, as inflammation can also reduce serum albumin level." (PMID 36059659, 2022). "Albumin, which is widely used as an index of malnutrition, was not significantly different between the conditions, but its level does not change in acute phases." (PMID 36129200, 2022). "In this regard, we assessed the patients’ dietary intake, although we did not study the link between liver enzymes and markers of malnutrition, except albumin." (PMID 34644766, 2021). "This is not surprising because albumin plays an important role in inflammation and suggests a state of malnutrition of patients." (PMID 33397522, 2021). "Lower ALB, serum CHOL, and TGs are key factors in anaemia and may represent a state of malnutrition in the body, which is also closely related to anaemia because of chronic inflammation in CKD." (PMID 34013043, 2021). "Unlike albumin levels, which are influenced by various factors such as inflammation, chronic kidney disease, or malnutrition, CHE is less subject to fluctuations and therefore a reliable marker of liver function." (PMID 34441964, 2021). "The results showed that the ALB of the malnutrition group was lower than that of the patients without malnutrition, but the difference was not statistically significant." (PMID 34702196, 2021). "The gain in FIM was significantly higher in patients at low risk of malnutrition (according to the Short Nutritional Assessment Questionnaire, SNAQ), in those who did not lose weight, had normal albumin, and lower CIES-G scores." (PMID 33809573, 2021). "Other examples include the Malnutrition Screening Tool, Short Nutritional Assessment Questionnaire and the recently developed Pre-operative Nutrition Score, which is a modification of MUST that also incorporates albumin." (PMID 34433498, 2021). "It is important that the perioperative clinician is aware that albumin reflects disease severity and related catabolism, and is not a direct measure of malnutrition." (PMID 34433498, 2021).
malnutrition (continued). "Although parenteral nutrition and erythropoietin were started on October 20, 2000 because of severe malnutrition and intestinal sub-occlusion, neither albumin and β-carotene serum levels nor hematologic parameters improved, and ascites increased." (PMID 37744114, 2021). "Case 5 had marked changes in status from the first to the second trimesters, developing severe hypertension (BP changed from 108/73 to 175/105 mmHg) and severe malnutrition (BUN from 63 to 35 mg/dL, albumin from 3.2 to 2.2 mg/dL, and phosphate from 5.1 to 2.5 mg/dL)." (PMID 34591251, 2021). "Malnourished patients were significantly older, and had lower BMI, waist circumference, and serum albumin level, and higher serum pro-adrenomedullin and D-dimer than patients without malnutrition." (PMID 34836338, 2021). "Hypoalbuminaemia is an important marker of severe malnutrition but is not a reliable indicator of nutritional status when an infection is present as albumin is a negative acute phase protein." (PMID 34394968, 2021). "Serum albumin is a negative acute-phase protein with antioxidant effects and an important marker of malnutrition." (PMID 33450916, 2021). "Since malnutrition prevalence was also generally low (F: 2%, M: 4%), validation of albumin utility was not feasible." (PMID 33673556, 2021). "Anomalies arise from malnutrition diagnosis that adopts body mass index (BMI) and serum albumin cut-offs, as muscle and fat compartments of the body are not differentiated, and albumin values are influenced by the presence of inflammation." (PMID 34977109, 2021). "Although ALB, PA, and TP did not change statistically, they all showed increasing trends, suggesting that nutritional treatment helps improve the malnutrition status of poor immune reconstitution patients." (PMID 35003070, 2021). "Based on correlation analysis of logGDF-15 with other serum biomarkers of malnutrition/inflammation, there was a negative correlation between the serum creatinine, serum potassium, and serum albumin levels." (PMID 34247467, 2021). "Concerning simple parameters of malnutrition, we found significant correlations with albumin, but not with BMI." (PMID 32709104, 2020). "Although albumin does not adequately correlate with malnutrition in the presence of inflammation, it is still a strong indicator of risk for morbidity and mortality in these cases." (PMID 32049129, 2020). "As a nutrition-related risk index, GNRI is different from BMI in increasing the weighting of albumin rather than body weight, thus to differentiate malnutrition patients with high BMI and well nutrition patients with low BMI." (PMID 33569000, 2020). "Malnutrition is highly prevalent among hepatic alveolar echinococcosis (HAE) patients, and the nutritional status of HAE patients is related to many clinical factors, such as Child-Pugh classification of liver function, lesion size, and serum albumin." (PMID 32092109, 2020). "In our study, serum albumin and creatinine levels, which are important parameters for malnutrition, were similar in PPD-positive and -negative HD and PD groups." (PMID 32323130, 2020). "Albumin level and MNA were used as markers of nutritional status and malnutrition." (PMID 33008315, 2020). "Since CONUT was based on the serum albumin level, total cholesterol level and total lymphocyte count, the CONUT score could reflect the malnutrition and systemic inflammation status." (PMID 32313183, 2020). "We found respective correlations between NGAL and Ca, P, Ca*P, ALB, and HDL‐C, which showed that NGAL may participate in the calcium and phosphorus metabolic disorders and malnutrition of CKD." (PMID 32232190, 2020). "The synthetic function remains intact, as evidenced by the absence of an effect on the coagulation profile and serum albumin levels, except when malnutrition occurs." (PMID 32699704, 2020). "Studies in children with severe malnutrition have shown that plasma albumin concentration was modulated by catabolic rates rather than synthesis rates." (PMID 32776978, 2020).
malnutrition (continued). "Fourth, although our study participants were generally healthy adults from a community-based cohort, we cannot guarantee no confounding effect due to acute infection or malnutrition influenced serum albumin and globulin concentrations." (PMID 32877465, 2020). "Based on the biochemical profile at admission serum sodium, potassium, albumin, CRP levels and haemoglobin were lower in patients at malnutrition risk compared to patients with no risk for malnutrition (p<0.2)." (PMID 30677081, 2019). "Available data suggests that hypoalbuminemia can be more appropriately viewed as a composite marker which reflects malnutrition, atherosclerosis as well as increased acute phase inflammation, considering that albumin is also a negative acute phase reactant." (PMID 30617956, 2019). "Because the protective effect of obesity remained significant after adjusting for AD albumin, a normal BMI does not appear to reflect malnutrition." (PMID 31337801, 2019). "Serum concentration of albumin, ALP and urea could reflect the effects of diet, since working equids often have malnutrition." (PMID 31781585, 2019). "Conditions such as malnutrition and liver failure might affect DBP, albumin, and other liver-specific protein status." (PMID 30972023, 2019). "Our study showed that patients with NCMS had lower hemoglobin, serum albumin, and total triglyceride levels than patients with UBMI, which might be a consequence of malnutrition due to a lower economic status in rural areas." (PMID 31880213, 2019). "In addition, we observed that malnutrition induced by NEAA-100% and EAA-30% diets led to a decrease in serum hemoglobin and albumin values." (PMID 31216646, 2019). "Also hypoalbuminemia, which is often present in the ESRD as a result of inflammation, malnutrition, etc., possibly contribute to lower serum HDL levels due to the fact that HDL receives a considerable amount of its cholesterol content from albumin." (PMID 31752189, 2019). "Meanwhile, serum albumin is a more potent predictor for survival, even reflecting disease severity rather than malnutrition." (PMID 31561559, 2019). "Albumin concentration is no longer considered as a good marker of malnutrition and few studies have correlated albumin with protein mass." (PMID 31194755, 2019). "Determinants of the non-prescription of ACEI or ARB included malnutrition (serum albumin levels < 35 g/L) (OR: 0.74 (95% CI: 0.57–0.95)) and eGFR between 30 and 50 ml/min (OR: 0.64 (95% CI: 0.45–0.91)) and eGFR < 30 ml/min (OR: 0.46 (95% CI: 0.32–0.67))." (PMID 31370798, 2019). "Because serum albumin is a commonly used marker for diagnosing malnutrition, we used GPS rather than mGPS in this study." (PMID 29899304, 2018). "Because conventional body mass index (cBMI) does not reflect fluid accumulation, modified BMI (mBMI, serum albumin multiplied by cBMI) is a more accurate measure of malnutrition status." (PMID 29652842, 2018). "A shortcoming in relying on albumin alone to identify malnutrition, without validating with BMI and dietary intake, is the risk of potential false negatives arising from inflammation, fluid overload and infection." (PMID 30514284, 2018). "Last, information on other dysphagia-related outcomes such as malnutrition, body weight or albumin levels were not collected in the trial." (PMID 28770403, 2018). "No patients presented with a high degree of malnutrition, according to the concentrations of albumin and prealbumin." (PMID 29324682, 2018). "Nevertheless, the mean BMI values in both groups were within reference values, excluding severe malnutrition, as confirmed by the higher albumin concentrations than the alert blood values, not significantly different between both groups." (PMID 29377934, 2018). "The correlation is probably not explained by colinearity (MIS integrates albumin, but albumin level accounts for only 10% of the malnutrition inflammation score)." (PMID 29986663, 2018).